SOD2 (superoxide dismutase 2)
Diseases named in the same sentence as SOD2 in open-access papers (continued):
Sharing a sentence is not in itself a finding about the gene and the disease.
tumor (continued). "Given that the tumor cells with TIC features are prone to withstand treatment, and given the crucial role of SOD2 in the regulation of ROS, we hypothesized that up-regulation of SOD2 is important for GBM to acquire TMZ resistance and is associated with enhancement of the TIC features." (PMID 31629402, 2019). "This cascade promotes cellular survival in non-neuronal tumor cells, through activation of I kappaB kinase (IKK) and nuclear factor-kappaB (NF-κB) that induces SOD2 transcription, a gene encoding the mitochondrial manganese-dependent superoxide dismutase (MnSOD) involved in ROS detoxification." (PMID 29273751, 2017). "Whether or not tumor cells are able to circumvent this mode of SOD2 inactivation, as a mechanism for apoptosis resistance, has not been explored." (PMID 29099803, 2017). "This was based on observations that SOD2 expression is decreased in some tumors compared to their normal tissue counterparts and that forced overexpression of SOD2 significantly delayed tumor cell growth in nude mice xenograft studies of several tumor types." (PMID 29099803, 2017). "Under these circumstances, SOD2 does not act as a tumor suppressor gene." (PMID 24690091, 2014). "SiRNA knockdown of SOD2 expression significantly reduced mean TrkAIII SH-SY5Y tumour spheroid volume but, unlike GW441756, did not reduce Nanog, Nestin, SOX2 or CD117 expression in tumor spheroids, implicating SOD2 in the promotion of SH-SY5Y tumour spheroid growth and survival but not staminality." (PMID 24736663, 2014). "However, under stress conditions such as aging or tumor progression, an increase in SOD2 expression not only fails to provide further protection but also promotes oxidative stress in mitochondria; thus, SOD2 has an important pro-oxidant effect in cells and in vivo." (PMID 40584154, 2025). "However, we did not note the effect of tumour progression on the status of SOD2 methylation." (PMID 37660159, 2023). "Thus, it appears that SOD2 is essential for the stimulation of MMP-1 as well as other MMP family members via the H2O2-dependent activation of MAPK signaling, resulting in the remodeling and degradation of the ECM and the basement membranes, thereby promoting tumor cell invasion and metastasis." (PMID 35164076, 2022). "Moreover, further analysis of the A375 tumors treated with A922500 revealed increased SESN2, SOD1, and SOD2 expression, concomitant with increased lipid peroxidation, confirming that our A922500 administration had been effective in inducing ROS and NRF2 signaling in tumor cells in vivo." (PMID 35732120, 2022). "However, they did not compare SOD2 genotype in the paired tumor and normal samples." (PMID 24498107, 2014). "We then performed immunoblotting analysis of SOD2 pS27 in confined A549 cells with or without IGFBP1 depletion, showing that IGFBP1 depletion increased SOD2 pS27 in confined tumor cells." (PMID 37296072, 2023). "In addition, considering that ALDEFLUOR cannot represent all tumor-initiating cells in HNC, the lack of SOD2 and resistance data in terms of the other selecting methods with CD44 or CD133 biomarkers is also a concern." (PMID 34681918, 2021). "Moreover, this MnP is preferentially distributed to tumor relative to non-tumor tissues, and it accumulates predominantly in mitochondria, thus mimicking SOD2 (MnSOD)." (PMID 31627290, 2019). "To characterize the role of SOD2 in human cancer, we examined the expression profile of SOD2 in matched pairs of tumor and adjacent non-tumor tissues in 14 different human cancer types from the cancer genome atlas (TCGA) PANCANCER dataset with SOD2 data (n = 5599)." (PMID 30103475, 2018).
cancer (384 papers, 1998 to 2025). A tumor composed of atypical neoplastic, often pleomorphic cells that invade other tissues. "In some tumors, elevated SOD2 activity has been linked to resistance to therapies such as radiation, which depends on ROS-induced damage to kill cancer cells." (PMID 39860164, 2025). "Prognostically relevant epithelium-specific cancer-associated fibroblasts (eCAFs) and SOD2+ inflammatory CAFs (iCAFs) predominated in EEC-I and UCCC groups, respectively." (PMID 39112478, 2024). "SOD2 gene regulation in cancer cells depends on mutations, epigenetic processes, and the expression of repressive transcription processes." (PMID 39040459, 2024). "They showed that deletion of the gene encoding SOD2 results in a decrease in its expression and thus in the migration and proliferation of cancer cells." (PMID 39195258, 2024). "For example, polymorphisms in genes related to antioxidant enzymes such as superoxide dismutase (SOD2) have been linked to varying responses to dietary antioxidants like vitamin C and E, influencing cancer risk." (PMID 39553634, 2024). "There is accumulating evidence connecting the GPX1 and SOD2 genetic variants with cancer development, disease progression, and treatment outcomes in a different types of cancers." (PMID 36676755, 2023). "SOD2 is easily regulated by transcription factors during cancer progression, and also a polymorphism present in the population is able to decrease its activity by 30–40%." (PMID 35204196, 2022). "The excessive expression of SOD2 in cancer cells is associated with increased expression of MMPs, inducing ECM degradation and metastasis progression." (PMID 36497431, 2022). "Genetic variations in SOD2 have been found to be associated with many diseases, including neurodegeneration, mitochondrial dysfunction, premature aging, angiogenesis, and cancer." (PMID 35164076, 2022). "This review will focus on the findings supporting the underlying mechanisms associated with the oncogenic potential of SOD2 in the onset and progression of cancer, especially in BC and the potential clinical relevance of its various inhibitors." (PMID 35164076, 2022). "Elevated SOD2 is associated with unpleasing prognosis, metastasis, and malignant progression of diversified cancers." (PMID 35543376, 2022). "SOD2 expression increases the cellular oxidant/antioxidant ratios, associated with cancer progression and metastasis." (PMID 36497431, 2022). "Of these isoforms, SOD2, encoded by the nuclear gene located on chromosome 6q25.3, was found to modify cancer susceptibility, largely due to several functional single nucleotide polymorphisms." (PMID 34200699, 2021). "As overexpression of HNF1B and SOD2 confers resistance to oxidative stress in cancer cells, OCCCs possess strong resistance to oxidative stress caused by cancer treatments such as chemotherapy." (PMID 33525614, 2021). "In agreement with the results of this study, most studies of SOD2 expression relative to cancer showed that high expression of the protein is associated with the presence of metastases and a dire prognosis in some malignancies." (PMID 34062984, 2021). "Inhibition of TSC2 in RB1-deficient cancer cells increased oxidative stress in a superoxide dismutase 2 (SOD2)-dependent manner, causing apoptosis." (PMID 34359636, 2021). "Previous studies have investigated the correlation between SOD2 V16A variant and the risk of cancer, with some of these reports indicating the correlation of this polymorphism with higher cancer risk." (PMID 31929112, 2020). "Interactions between the genotypes of GPX1 and SOD2, the gene encoding manganese superoxide dismutase, another antioxidant protein, also impact the regulation of proteins implicated in cancer progression." (PMID 32806741, 2020). "Loss of SOD2 expression can favor cancer cell progression mediated by increasing ROS-mediated DNA alterations." (PMID 32111081, 2020).
cancer (continued). "Till date, several studies have assessed the relationship between SOD2 V16A variant and cancer susceptibility; however, their conclusions remain inconsistent." (PMID 31929112, 2020). "A further point to note when considering an influence of PrP-mediated signalling on SOD2 is that aberrations in SOD2 expression are linked with the uncontrolled cell cycling of cancer cells." (PMID 29574582, 2018). "These include key biological stress response genes like GPXs, TXNRD3, SELENOS, SELENOH, and the related SOD2 gene implicated in cancer cell survival, and genes such as SELENOP and SEPHS2 involved in Se biosynthesis." (PMID 30469315, 2018). "Increased levels of SOD2 have been linked to increased metastatic capability by enabling cancer cells to maintain an increased growth potential and stay protected from excess ROS that would otherwise lead to apoptosis and necrosis." (PMID 29731978, 2018). "Several studies have reported epigenetic regulation of the SOD2 gene in both transformed and cancer cells, including SOD2 promoter methylation and association with repressive histone modifications." (PMID 29099803, 2017). "Several studies have demonstrated the correlation between ALDH2 gene or SOD2 gene polymorphisms and susceptibility to cancer development." (PMID 28841898, 2017). "Given that the SOD2 gene is rarely lost or mutated in cancer points to the fact that SOD2 regulation is adaptable." (PMID 29099803, 2017). "Epigenetic regulation of SOD2 transcription is primarily associated with decreased SOD2 expression in cancer." (PMID 29099803, 2017). "Some studies suggest that the SOD2 polymorphism acts as a predictor of response to chemotherapy in cancer patients." (PMID 24498107, 2014). "Nevertheless, association of Val form of SOD2 with higher cancer was reported only in a very few studies." (PMID 24587799, 2014). "In order to further test the validity of this model and its dependence on mitochondrial oxidative stress, Capozza, Lisanti, and colleagues over-expressed mitochondrial SOD2 in cancer associated fibroblasts." (PMID 21605374, 2011). "Another area of research for MnSOD in cancer development is the effect of single nucleotide polymorphisms (SNPs) in the SOD2 gene that alter the overall expression, function, or subcellular localization of MnSOD." (PMID 22072939, 2011). "The importance of SOD2 -9T/C polymorphism is indicated by its association with several age related diseases such as cancer and diabetic nephropathy." (PMID 20003469, 2009). "Some studies have associated low SOD2 activity with poor prognosis, whereas others have suggested that higher SOD2 activity is associated with worse outcomes in gastric, esophageal, breast, lung, cervical, and penile cancers." (PMID 40244057, 2025). "Many studies on SOD2 have also reported an association with cancer." (PMID 40244057, 2025). "Reduced SOD2 expression levels might lead to ROS accumulation, which can increase the risk of cancer development." (PMID 40244057, 2025). "SOD2 deficiency triggers metabolic adaptation in cancer cells by increasing ROS and peroxynitrite." (PMID 41353397, 2025). "Therefore, we preliminarily defined c4_SOD2 as suppressive cancer-associated pericytes (sup-CAPs) and c5_TYMS as promoted cancer-associated pericytes (pro-CAPs)." (PMID 39835116, 2024). "Additionally, regulation of SOD2 has been implicated in cancer, metabolic and neurodegenerative diseases, and aging." (PMID 37839702, 2023). "Therefore, TMZ resistance in mesenchymal GBM was associated with aberrant CYBB expression, Nrf2/SOD2 mitochondrial antioxidant axis activation, and cancer stemness properties." (PMID 37175412, 2023). "SOD2 plays a role in the mitochondrial antioxidant system and a reduction in SOD2 activity has already been associated with increased oxidative levels and cancer potential." (PMID 36119129, 2022). "Some variants of the SOD2 gene have been associated with cancer." (PMID 36354667, 2022).
cancer (continued). "We believe that measuring the circulating levels of SOD2 during therapeutic treatment of advanced cancer patients could offer a simple, non-invasive diagnostic tool complementing standard imaging techniques." (PMID 36010852, 2022). "Furthermore, high levels of ROS and RNS appear to play complex roles in cancer development due to metabolic abnormalities and life‐long reductions in the mitochondrial SOD2 enzyme were associated with increased DNA oxidative damage and cancer incidence." (PMID 35581738, 2022). "Different mechanisms have been proposed for the loss of SOD2 in cancer." (PMID 35164076, 2022). "Moreover, two studies showed a statistically significant interaction between SOD2 with dietary intake of vitamin E and selenium affecting the risk of cancer." (PMID 35646794, 2022). "The valine (T allele) form of SOD2 rs4880 results in faulty protein that partially traps in the inner mitochondrial membrane resulting in lower enzymatic efficiency and high likelihood of cancers and toxicities." (PMID 34887513, 2021). "Because previous reports have shown associations between SOD2 and the cancer stemness features, we postulated the treatment could have adverse effect in bringing cell tolerance, and hence, selecting subgroups of stem-like cells that impede further treatment." (PMID 34681918, 2021). "In addition, accumulating studies have indicated a correlation between the SOD2 V16A variant and risk of cancer." (PMID 31929112, 2020). "Mutations in the SOD2 gene are associated to various types of cancer." (PMID 32111081, 2020). "As SOD2 is an antioxidant enzyme that can prevent oxidative redox-mediated damage of mitochondrial proteins and preserve mitochondrial function, EAOC with high SOD2 expression likely have strong resistance to oxidative stress caused by cancer treatment such as chemotherapy." (PMID 30700285, 2019). "In previous studies, high SOD2 expression is associated with poor prognosis in some carcinomas." (PMID 30700285, 2019). "In addition to changes in mitochondrial SOD2, changes in mitochondrial fission and fusion have been linked with the uncontrolled cell cycling during cellular adaptation to the energy demands of cancer." (PMID 29574582, 2018). "One potential cause of dysregulation of SOD2 expression in cancer is mediated through miRNA." (PMID 29099803, 2017). "SOD2 Ala16Val SNPs have been found to correlate variably with different cancer susceptibility." (PMID 26881045, 2016). "Analysis of SOD2 expression conducted in solid tumor samples including colorectal, gastric and esophageal, oral, lung, brain, cervical and skin carcinomas have often associated its up-regulation with metastasis and poor disease outcome." (PMID 25745358, 2015). "Polymorphic variants of SOD2 have been demonstrated to be factors that may enhance the risk of cancer development." (PMID 24348785, 2014). "Carriage of one or two Ala-SOD2 alleles is reportedly associated with a greater risk of cancer." (PMID 24348785, 2014). "However, invivo studies with Sod2 mutant mice have shown that Sod2haploinsufficiency can increase the level of oxidative modification to nuclearDNA and increase the cancer risk in very old (26 month old mice)." (PMID 20195488, 2009). "SOD2 polymorphisms, including isoleucine-to-threonine substitution at amino acid 58 (Ile58Thr), which destabilized tetramer formation, and leucine-to-phenylalanine at codon 60 (Leu60Phe), result in decreased SOD2 activity and have consequences on cancer malignancy." (PMID 29099803, 2017). "Our data reveal that SOD2 is overexpressed in quiescent PCa cells, which is in line with observations in other cancer types." (PMID 40520023, 2025). "This SOD2-driven protein breakdown enhances cancer cell survival upon starvation by creating an alternative source of amino acids." (PMID 40131931, 2025).
cancer (continued). "We propose a model in which the interaction of SOD2 and UBRs can adaptively trigger protein breakdown as an independent catabolic source of amino acids, a mechanism co-opted by cancer cells to maintain cellular fitness upon starvation." (PMID 40131931, 2025). "Based on these observations, we aimed to further investigate the impact of Sod2 deletion in established cancer cell lines." (PMID 41353397, 2025). "We propose that, in response to amino acid depletion, cancer cells can trigger protein degradation through the SOD2-UBR interaction as a catabolic source of amino acids to promote cell survival." (PMID 40131931, 2025). "Does the inhibition of SOD2 mediate cancer cell sensitivity to amino acid starvation by inhibition of protein degradation?" (PMID 40131931, 2025). "To test the idea that SOD2-mediated proteasomal protein degradation reflects a compensatory mechanism for cancer cells, we generated WNT/STOP-resistant T-ALL single-cell clones." (PMID 40131931, 2025). "In quiescent PCa cells, SOD2 protein and mRNA levels were significantly elevated than those in proliferative cancer cells, and these levels decreased during the awakening process." (PMID 40520023, 2025). "In cancer cells, mitochondrial superoxide dismutase (MnSOD, also known as SOD2) similarly guards Wnt signaling." (PMID 41009046, 2025). "New SOD-2 mimetics have been developed to reduce OS after radiotherapy in cancer patients, Avasopasem Manganese (GC4419 AVA), that selectively reduces superoxide dismutase and peroxide." (PMID 39334797, 2024). "This potentiates SOD2 to be a reliable cancer biomarker and a promising anti-cancer target in NSCLC." (PMID 38082189, 2024). "MALAT1 and SOD2 were universally expressed across all these cell types while KRT19 demonstrated higher expression in cancer and Ascending Thin Limb of Loop of Henle cells (LoH ATL cells)." (PMID 38431724, 2024). "Compensatory antioxidant SOD2 further protects against cytotoxicity induced by high ROS levels during ferroptosis in these temozolomide-resistant cancer cells." (PMID 39624080, 2024). "SOD2 scavenges superoxide radicals formed in the respiratory electron transport chain, thereby impacting cell cycle signaling and cancer progression." (PMID 38535948, 2024). "Cell–cell communication analysis indicated that the L-R pairs of EFNA1-EPHA2/4, EFNA5-EPHA2/4, EFNB2-EPHA4, and EFNB2-EPHB1/2 were particularly enriched in SOD2+ iCAFs and other cell types, which are known to facilitate metastasis in malignant tumors." (PMID 39112478, 2024). "In the pioneering work by Oberley and Buettner published more than four decades ago, these authors suggested for the first time the importance of suppressed SOD2 (Mn-SOD) expression in cancer." (PMID 38483584, 2024). "The increase in SOD-2 activity protects cells against oxidative stress and influences cancer development." (PMID 38247462, 2023). "The overexpression of scavenger SOD2 was able to normalize superoxide levels while increasing hydrogen peroxide levels in favor of cancer cell growth, which resulted in decreasing the effect of NB." (PMID 37891871, 2023). "The interpretation of our findings is consistent with the evidence of the dual role of SOD2 in cancer development." (PMID 36676755, 2023). "This combination induces oxidative stress-mediated apoptosis in cancer cells through the inhibition of the SIRT3/SOD2-Akt (SIRT3: sirtuin-3, SOD2: superoxide dismutase 2, Akt: serine/threonine kinase 1) pathway." (PMID 37630248, 2023). "SOD2 has also showed differential expression in different cancers such as cervical, lung, brain, colon, breast, gastric and salivary cancer." (PMID 36809279, 2023). "On the other hand, a relative decrease in the amount of hydrogen peroxide due to reduced SOD2 activity will deprive the cell of the stimulus initiating apoptosis, thus allowing it to survive and transform into a cancer cell." (PMID 37660159, 2023).